TSLP (thymic stromal lymphopoietin)
Diseases named in the same sentence as TSLP in open-access papers (continued):
Sharing a sentence is not in itself a finding about the gene and the disease.
Pruritus (continued). "Thymic stromal lymphopoietin (TSLP) and IL-31 are Th2 cytokines that induce pruritus by activating cutaneous somatosensory neurons either directly or indirectly through the stimulation of immune cells." (PMID 37958804, 2023). "The TSLP-induced itch also required TRPA1, with the expression and release of keratinocyte-derived TSLP depending on the ORAI1/NFAT calcium signaling pathway." (PMID 34830245, 2021). "Overall, the results demonstrated that the cutaneous neuroimmune interactions of TSLP and TRPV4 play pivotal roles in dry skin-induced pruritus." (PMID 34925342, 2021). "The present study suggests the importance of TSLP and TRPV4 in dry skin conditions and identified potential molecular targets for dry skin-induced pruritus." (PMID 34925342, 2021). "In a LEKTI-knockout mouse model, increased kallikrein-5 stimulated proteinase-associated receptor-2 (PAR2), which activates nuclear factor κ B-induced overexpression of thymic stromal lymphopoietin (TSLP) and induces pruritus." (PMID 27483258, 2016). "Interestingly, cultured murine keratinocytes carrying the mutation krt14 R131P, homologous to the human KRT14 R125P, revealed up-regulation of the cytokine thymic stromal lymphopoietin (TSLP), which correlates with pruritus." (PMID 40700032, 2025). "On the other hand, an immunohistochemical study has demonstrated that TSLP levels in the lesional epidermis do not correlate with pruritus severity." (PMID 36477831, 2023). "However, the relationship between TSLP expression levels and CTCL pruritus are, as of yet, unclear and need further exploration." (PMID 37555911, 2023). "Further research is expected to determine whether the combination of TRPV3 with TSLP and PAR2 inhibitors can provide a feasible solution for PS pruritus." (PMID 37705977, 2023). "While this generates a positive feedback loop of enhanced TSLP production, TSLP can also activate the innervated peripheral sensory neurons through TSLPR and TRPV4, thereby producing electrical signals for the onset of pruritus." (PMID 34925342, 2021). "However, the relationship between TSLP and TRPV4 in dry skin-induced pruritus remains to be investigated." (PMID 34925342, 2021). "In this study we demonstrated the relationships of PAR2, TRPV3 and TSLP in keratinocytes from scars with or without pruritus." (PMID 29140280, 2017). "In order to compare the expression of TSLP and TSLPR in normal and burn-scar tissues with or without pruritus, we measured the mRNA level of TSLP in the tissues using qPCR." (PMID 29140280, 2017). "The levels of total IgE and TSLP were considerably increased in patients with MF, regardless of whether these patients experienced current pruritus or not." (PMID 39068637, 2024). "PS pruritus may be related to the expression of PAR2 and TSLP, which is mediated by TRPV3 channels." (PMID 37705977, 2023). "The findings of our study could be of great significance in explaining the role of TSLP because it might play an important role in the pathogenesis of post-burn pruritus and, although not focused on in this study, burn-scar formation." (PMID 29140280, 2017). "Therefore, the expression of TRPV3 in PS may be positively correlated with the degree of pruritus, and the upregulation of TRPV3 channels may be related to the increased expression of PAR2 and TSLP and the involvement of the PAR2-TSLP positive feedback pathway." (PMID 37705977, 2023). "In addition, TRPV3-mediated PS pruritus may be related to the expression of PAR2 and TSLP." (PMID 37705977, 2023). "TSLP mRNA and protein, and TSLPR protein expressions, increased in scars with post-burn pruritus, compared to scars without it or to normal tissues." (PMID 29140280, 2017).
allergic rhinitis (45 papers, 2011 to 2025). Inflammation of the nasal mucous membranes caused by an IgE-mediated response to external allergens. "Genetic analysis has shown an association of TSLP polymorphism with a higher risk for allergic rhinitis." (PMID 30057581, 2018). "Moreover, it has been demonstrated that the increased expression of TSLP in nasal epithelial cells of patients with allergic rhinitis can be associated with developing nasal polyps." (PMID 39940994, 2025). "The epithelial-derived factor TSLP is an IL-7-like cytokine that potently induces deregulation of Th2 responses, a hallmark feature of allergic inflammatory diseases such as asthma, atopic dermatitis, and allergic rhinitis." (PMID 23509817, 2013). "Moreover, TSLP polymorphisms appear to be associated with a higher risk of allergic rhinitis." (PMID 30057581, 2018). "Increased TSLP expression in nasal epithelial cells among those with nasal comorbidities, although not significant, is also consistent with previous studies in allergic rhinitis and chronic rhinosinusitis." (PMID 38999286, 2024). "In allergic rhinitis, TSLP plays a central role in the initiation and persistence of allergic responses." (PMID 37628907, 2023). "Studies on the levels of alarmins in patients with allergic rhinitis have shown that levels of IL-33, IL-25, and TSLP are significantly higher compared to healthy controls." (PMID 35406669, 2022). "Catechin reduces expression of TSLP (thymic stromal lymphopoietin) and NF-κBp65 in the nasal mucosa of mice with allergic rhinitis." (PMID 35745226, 2022). "TSLP expression in the nasal epithelial cells of patients with allergic rhinitis is found to be significantly greater than that in the nasal mucosa of patients with nonallergic rhinitis." (PMID 35378908, 2022). "Airway epithelium plays an important role during the development of allergic rhinitis (AR), which is characterized by production of thymic stromal lymphopoietin (TSLP), interleukin 33 (IL-33), and interleukin 25 (IL-25)." (PMID 34899052, 2021). "Proinflammatory cytokine thymic stromal lymphopoietin (TSLP) is perceived as a pivotal factor in the pathogenesis of atopic diseases such as AD and allergic rhinitis." (PMID 30991764, 2019). "There was a higher production profile of TNF-α and TSLP in nasal secretion in the patients with perennial allergic rhinitis and additional high sensitization to SEs." (PMID 29109963, 2017). "This compound inhibited allergic responses via the regulation of the production of IL-32 and thymic stromal lymphopoietin and nasal mucosa caspase-1 activity in a murine allergic rhinitis model." (PMID 26694364, 2015). "We found high expression of TSLP in epithelium from patients with allergic rhinitis with recruitment and infiltration of CD11c+ DCs." (PMID 23509817, 2013). "A few in vitro and murine studies with small sample size have examined TSLP expression in allergic rhinitis (AR)." (PMID 21244681, 2011). "Recently it was reported that inhibition of TSLP using tezepelumab increases the efficacy of subcutaneous allergen immunotherapy in patients with allergic rhinitis to cats and may promote tolerance after a one-year course of treatment." (PMID 37628907, 2023). "Mast cells, in turn, can regulate epithelial TSLP expression in allergic rhinitis." (PMID 34571811, 2021). "The nasal epithelial-derived TSLP not only activates DCs but also preserves the epithelial barrier via upregulation of tight junction proteins to regulate antigen sensitization during the early stage of allergic rhinitis." (PMID 23509817, 2013). "MC deficient mice failed to upregulate TSLP in nasal epithelium after allergen challenge in a model of allergic rhinitis." (PMID 22876248, 2012). "AEC activated with various stimuli produce TSLP which may induce IL-13 release from cultured mast cells derived from peripheral blood progenitors, and mast cells are required for epithelial TSLP expression in a model of allergic rhinitis." (PMID 22970103, 2012).
allergic rhinitis (continued). "A human monoclonal anti-TSLP antibody (tezepelumab) improved SCIT efficacy and enhanced tolerance in allergic rhinitis patients in a 1-year therapy course." (PMID 40266074, 2025). "A one-year anti-TSLP (tezepelumab) therapy course initiated an allergic response with improved SCIT efficacy and tolerance in allergic rhinitis patients." (PMID 40266074, 2025). "The relative mRNA expressions of TSLP, TSLPR, OX40, OX40L, and IL-7R in the nasal mucosa of allergic rhinitis mice were considerably higher than those in the control group." (PMID 36172190, 2022). "After using an IL-9 neutralizing antibody, the mRNA expression of TSLP, TSLPR, OX40, OX40L, and IL-7R decreased significantly compared with the allergic rhinitis group, and the difference was statistically significant." (PMID 36172190, 2022). "After using an IL-9 neutralizing antibody, the mRNA expression of TSLP, TSLPR, OX40, OX40L, and IL-7R decreased significantly compared with the allergic rhinitis group." (PMID 36172190, 2022). "Firstly, we detected the relative mRNA expression of TSLP, TSLPR, OX40, OX40L, and IL-7R in the nasal and sinus mucosa of allergic rhinitis mice by real-time PCR." (PMID 36172190, 2022). "The relative expressions of TSLP, TSLPR, and IL-7R in the nasal mucosa of allergic rhinitis mice were significantly higher than those in the control group." (PMID 36172190, 2022). "Tezepelumab, a human mAb anti-thymic stromal lymphopoietin (TSLP), enhances the efficacy of SCIT in cat-triggered allergic rhinitis patients and may promote tolerance after a 1-year course of treatment." (PMID 38143940, 2023). "In addition, epithelial-derived thymic stromal lymphopoietin (TSLP), which is a master switch for allergic inflammatory diseases including allergic rhinitis, enhances the barrier function together with an increase of tight junction molecules in HNECs." (PMID 23509817, 2013). "This study assessed the mRNA expression levels of various tight junctions, including occludin (OCLN), claudin-3 and −7 (CLDN3 and CLDN7), desmoglein 3 (DSG3), and thymic stromal lymphopoietin (TSLP) in 30 individuals with Allergic Rhinitis (AR) and 30 non-allergic controls." (PMID 37692890, 2023).
food allergy (43 papers, 2013 to 2026). Gastrointestinal disturbances, skin eruptions, or shock due to allergic reactions to allergens in food. "Similarly, polymorphisms in the SPINK5 gene, which lead to abnormal skin keratinization and elevated levels of cytokines such as TSLP, are reported to be associated with food allergies." (PMID 40290033, 2025). "Furthermore, mutations in the gene encoding TSLP drive disease susceptibility and are associated with a major risk of food allergy development." (PMID 37048784, 2023). "Also, eosinophilic esophagitis, an inflammatory disease of the esophagus associated with food allergy characterized by esophageal eosinophilia, has been associated with TSLP gene polymorphisms." (PMID 26793299, 2015). "Recent work has characterised small intestinal tuft cells as being capable of producing TSLP when transcription factor Spi‐B is knocked out, and that this TSLP can play a functional role in both Hp immunity and food allergy." (PMID 40944312, 2025). "A number of biologics targeting ILC pathways, such as dupilumab (anti IL-4/IL-13 receptor), etokimab (anti-IL-33) and tepezulmab (anti-TSLP) have been trialled in food allergy and other atopic diseases [54▪,58,59]." (PMID 39132724, 2024). "The role of TSLP in the pathophysiology of IgE-mediated food allergy is also discussed in human studies." (PMID 37628907, 2023). "The existing evidence indicates that IL-33, IL-25 and TSLP induced by danger signals in tissues, are a key players in pathogenesis of epicutaneously induced food allergy 13,48]." (PMID 36904070, 2023). "Abrocitinib, an inhibitor of JAK1 that is part of the signaling complex downstream of a number of cytokine receptors including IL-4, IL-13, IL-9, and TSLP, is also in a phase I trial for the treatment of food allergy (NCT05069831)." (PMID 36880703, 2023). "Innate cytokines that drive type 2 immunity, namely TSLP, IL-33, and IL-25, have also been shown to be necessary for the development of food allergy in mouse models." (PMID 36880703, 2023). "TSLP has a critical role in TH2 responses during the sensitization phase of food allergy, while IL-33 is important in inducing IgE-dependent anaphylaxis." (PMID 37628907, 2023). "Epithelial-derived cytokines, including thymic stromal lymphopoietin (TSLP) and IL-33 have a pivotal role in the development of allergic response at the gut barrier surface which has been linked to the development of food allergy." (PMID 36660742, 2022). "Although information of direct induction of the production of IL-33 and TSLP by food allergens is sparse to date, several food allergens display proteolytic activity, and the role of these cytokines in the development food allergies is well established." (PMID 36660742, 2022). "The epithelial cell-derived cytokines IL-33, IL-25, and TSLP are central regulators of type 2 immunity, which promotes a wide array of allergic responses, including food allergies." (PMID 36429158, 2022). "The gut epithelial barrier is also known to play a role in the pathogenesis of food allergy, largely through antigen uptake and cytokine production (TSLP, IL-33, and IL-15)." (PMID 36263023, 2022). "The upstream role of IL-33 and TSLP in promoting Th2 responses makes them interesting targets for the treatment of atopic conditions, including food allergy." (PMID 34456900, 2021). "In a food allergy mouse model, TSLP participates in the skin sensitization to food antigens, promoting basophil recruitment and initiating Th2 responses, whereas IL-33 is essential for gut-mediated sensitization and effector responses, including anaphylaxis." (PMID 34456900, 2021). "Epithelial Type 2-inducing cytokines, such as IL-25, IL-33, and TSLP, are important drivers of inflammation in food allergy, however, most experimental studies have relied on whole body knockouts or systemic antibody-mediated neutralization in mice." (PMID 33365031, 2020).
food allergy (continued). "In short, activation of ILC2s by local epithelial cytokines IL-33 and TSLP has been shown to play a major role in the development of food allergy." (PMID 33333859, 2020). "In mice it was proven that only a cocktail of the three monoclonal antibodies against IL-25, IL-33, and TSLP can inhibit the development of food allergy in mice." (PMID 33333859, 2020). "Taken together, this suggests a critical role for IL-4 derived from TSLP-induced basophils in the sensitization to food allergens in the skin, and the development of food allergy." (PMID 33333859, 2020). "In mice with an atopic dermatitis-like skin, cutaneous food allergen sensitization induces an expansion of TSLP-elucidated basophils in the skin, which is sufficient to promote the development of IgE-mast cell mediated food allergy after oral antigen exposure." (PMID 33333859, 2020). "Activation of the NF-ĸB signaling pathway and release of epithelium-derived IL-33, TSLP, and IL-25 are observed in airway epithelium during the initiation of type 2 immune response in respiratory mucosa and in food allergy." (PMID 31810340, 2019). "Accumulating evidence from recent animal studies has further substantiated the roles of TSLP and allergic sensitization via skin barrier in the development of experimental food allergy." (PMID 27853507, 2016). "The immunological parameters correlated with a strong decrease of clinical reactivity upon oral antigen challenge reinforcing a strong dependency of food allergy on TSLP." (PMID 26793299, 2015). "Altogether, these results suggest that TSLP, in addition to other factors, intervenes in the pathogenesis of food allergy in the mouse models studied here." (PMID 26793299, 2015). "TSLP can be considered as a protein contributing to modulating food allergy in the mouse model described here." (PMID 26793299, 2015). "We explored the role of TSLP in a mouse model with oral sensitization and oral challenge eliciting food allergy." (PMID 26793299, 2015). "In the present research, we aimed to assess the associations of the TSLP gene single-nucleotide polymorphisms (SNPs) rs3806933 and rs10062929 with the risk of non-IgE-mediated food allergy, as well as with other characteristics of these patients." (PMID 42196468, 2026). "The overexpression of the IEC-derived cytokines TSLP and IL-33 is critical in food allergy." (PMID 29896198, 2018). "Also, IL-12 mediated suppression of food allergy was accompanied by the downregulation of the IEC-derived cytokine TSLP." (PMID 29896198, 2018). "Here we define TSLP as a new target for modulation of food allergy." (PMID 26793299, 2015). "Thymic stromal lymphopoietin (TSLP) dependant mechanisms of food allergy have also been suspected." (PMID 26793299, 2015). "New therapeutic strategies might consider including TSLP as a target for modulation of food allergy." (PMID 26793299, 2015). "Nevertheless, data on the role of TSLP in food allergy are scarce." (PMID 26793299, 2015). "Several investigations addressed the role of TSLP in food allergy." (PMID 26793299, 2015). "Epicutaneous sensitization to food allergen and development of food allergy may occur without skin inflammation and is partly mediated by TSLP, suggesting that its therapeutic targeting may be beneficial in food allergy early in life in at-risk infants." (PMID 37628907, 2023). "It has been also reported that polymorphism in the thymic stromal lymphopoietin (TSLP) gene and its receptor, as well as dysregulation of genes involved in the metabolism of epidermal lipids, are associated with an increased risk of AD, its resistance, and food allergy." (PMID 36765395, 2023). "Also, they found that TSLP in skin facilitated food allergy." (PMID 32973790, 2020). "Furthermore, IgE, Th2, TSLP, IL-25, and IL-33 might enter the digestive and respiratory tracts through blood circulation to facilitate the development of AA, AR, and food allergy if allergens are re-encountered." (PMID 32973790, 2020).
food allergy (continued). "In murine models of food allergy, oral exposure to antigen and an adjuvant stimulates gut epithelial cells to express the innate pro-allergenic IL-33, IL-25, and thymic stromal lymphopoietin (TSLP), which contribute to the development of acute reactions to food and promotion of Th2 response." (PMID 31810340, 2019). "Additional murine studies noticed that TSLP is an essential, but not exclusive, mediator in eliciting food allergy." (PMID 37628907, 2023). "In a mouse model of food allergy, neutralization of all Th2-driving cytokines IL-25, IL-33, and TSLP was necessary to suppress symptoms, but this was not performed in the context of OIT." (PMID 36880703, 2023). "Combined treatment with the antagonists of TSLP, IL-25 and IL-33 or with an inhibitor of pro-TH2 cytokine production might be able to suppress established human food allergy." (PMID 34301307, 2021). "In another study using a food allergy mouse model, blockade of IL-25, IL-33, or TSLP did not suppress established food allergies, and optimal food allergy suppression required treatment by combined blocking of all three cytokine signals." (PMID 32309281, 2020). "TSLP can be considered as an essential, but not exclusive, mediator for elicitation of food allergy in mice, as well as a potential target for future therapeutic interventions." (PMID 26793299, 2015). "However, no clinical studies assessing the efficacy of anti-TSLP treatment in food allergy are currently on-going." (PMID 34456900, 2021). "Experiments presented here clearly show that food allergy in mice induced after oral antigen sensitization in presence of CT followed by an oral antigen challenge is strongly, but not exclusively, dependent on a functional TSLP pathway." (PMID 26793299, 2015).